ZEB1 (zinc finger E-box binding homeobox 1)
Description:
Acts as a transcriptional repressor. Inhibits interleukin-2 (IL-2) gene expression. Enhances or represses the promoter activity of the ATP1A1 gene depending on the quantity of cDNA and on the cell type. Represses E-cadherin promoter and induces an epithelial-mesenchymal transition (EMT) by recruiting SMARCA4/BRG1. Represses BCL6 transcription in the presence of the corepressor CTBP1. Positively regulates neuronal differentiation. Represses RCOR1 transcription activation during neurogenesis. Represses transcription by binding to the E box (5'-CANNTG-3'). In the absence of TGFB1, acts as a repressor of COL1A2 transcription via binding to the E-box in the upstream enhancer region (By similarity).
Synonyms: AREB6; TCF8; BZP; ZEB; NIL-2-A; Zfhep; Zfhx1a; FECD6; DELTAEF1; NIL2A; PPCD3
Tractability: PROTAC: UniProt records ubiquitination sites on it; ubiquitination databases record sites on it.
Gene: Protein-coding gene on chromosome 10 (31,318,495 to 31,529,814, forward strand). Ensembl gene ENSG00000148516.
Subcellular location: Nucleus
Subcellular location (Human Protein Atlas): Nucleoplasm; Nucleoli
Pathways (Reactome):
Cell-Cell communication: Negative Regulation of CDH1 Gene Transcription
Developmental Biology: Regulation of MITF-M-dependent genes involved in extracellular matrix, focal adhesion and epithelial-to-mesenchymal transition
Immune System: Interleukin-4 and Interleukin-13 signaling
Gene Ontology:
Molecular function: DNA-binding transcription repressor activity, RNA polymerase II-specific; protein binding; DNA-binding transcription factor activity; DNA-binding transcription factor activity, RNA polymerase II-specific; E-box binding; RNA polymerase II cis-regulatory region sequence-specific DNA binding; zinc ion binding; chromatin binding; DNA binding
Biological process: negative regulation of DNA-templated transcription; negative regulation of endothelial cell differentiation; negative regulation of transcription by RNA polymerase II; central nervous system development; positive regulation of neuron differentiation; regulation of transcription by RNA polymerase II
Cellular component: nucleolus; nucleoplasm; nucleus; chromatin
Genetic constraint (gnomAD): Loss-of-function variants: 21 observed, 89.17 expected, observed/expected ratio (o/e) 0.24, 90% interval 0.17 to 0.34. The upper end of that interval is the gene's LOEUF score, 0.34, which puts it in group 1 of 6, group 1 being the genes least tolerant of losing a copy. Missense variants: 1,104 observed, 1,394.6 expected, observed/expected ratio (o/e) 0.79, 90% interval 0.75 to 0.83. Synonymous variants: 420 observed, 496.31 expected, observed/expected ratio (o/e) 0.85, 90% interval 0.78 to 0.92.
Homologues: Orthologues: macaque ZEB1 (99% identical), chimpanzee ZEB1 (99% identical), dog ZEB1 (93% identical), guinea pig ZEB1 (93% identical), pig ZEB1 (90% identical), mouse Zeb1 (86% identical), rat Zeb1 (86% identical), rabbit ZEB1 (82% identical), tropical clawed frog zeb1 (72% identical), zebrafish zeb1b (55% identical), zebrafish zeb1a (42% identical). Paralogues in human: ZEB2 (46% identical).
Diseases named in the same sentence as ZEB1 in open-access papers:
ZEB1 is named in the same sentence as 342 diseases in open-access papers, as found by Europe PMC text mining. Sharing a sentence is not in itself a finding about the gene and the disease. The quoted sentences say what the papers report.
breast carcinoma (710 papers, 2009 to 2026). "In breast cancer, the loss of miR-200c allows ZEB1-driven EMT and chemoresistance, while restoring miR-200c sensitises cells to docetaxel." (PMID 40806254, 2025). "Under in vitro and in vivo conditions, ZEB1 downregulation makes breast cancer cells more susceptible to chemotherapy." (PMID 40843360, 2025). "The activation of aerobic glycolysis by zinc finger E-box binding homeobox 1 (ZEB1) facilitates the polarization of M2-like tumor-associated macrophages, ultimately promoting breast cancer cell growth, metastasis, and chemoresistance." (PMID 40933952, 2025). "In breast cancer (BC), miR-561-3p has been shown to downregulate PD-L1 expression by repressing certain oncogenes associated with breast cancer such as ZEB1, HIF1A and MYC." (PMID 39941003, 2025). "In the GSE26304 dataset 35, NOTCH3 expression was positively correlated with OS (p = 0.0231, HR = 0.274), whereas ZEB1 expression was negatively associated with OS of breast cancer patients (p = 0.00365, HR = 6.43)." (PMID 38164285, 2024). "High Snail expression was found to cause pEMT in basal breast cancer cells and was essential for tumorigencity, but Zeb1 was required for complete EMT." (PMID 36788501, 2023). "For example, gene profiling screening and promoter analysis of Zeb1 showed that Crumbs3, Lgl2, and Pals1-associated TJ protein are all repressed by Zeb1 in breast cancer cell lines or colorectal carcinoma cells." (PMID 37853467, 2023). "ZEB1 expression has been linked to claudin-low and metaplastic breast cancer subtypes, both of which are more common in women of AA compared to women of EA21–24." (PMID 37709737, 2023). "ZEB1 is highly expressed in tumor tissues, including lung cancer, liver cancer, pancreatic cancer, colon cancer, and breast cancer, and is associated with tumor malignancy, particularly in breast cancer." (PMID 37978168, 2023). "In our breast cancer cell lines, we demonstrated that loss of ZEB1 reversed EMT and also substantially enhanced TROP2 expression." (PMID 37567892, 2023). "High levels of ZEB1 in invasive ERα– tumors are associated with the expression of genes suggested being involved in breast cancer bone metastasis." (PMID 35440541, 2022). "ZEB1/2 are highly expressed in aggressive basal‐like breast cancers associated with a poor prognosis, while being hardly expressed in the luminal‐type breast cancers associated with a good prognosis." (PMID 35451213, 2022). "MiR-708 downregulation in different breast cancer cell lines causes an increase in the expression of three of its direct targets, Zinc Finger E-Box Binding Homeobox 1 (ZEB1), Cadherin 2 (CDH2), and vimentin, which are known EMT inducers." (PMID 35011736, 2022). "For instance, ZEB1 binds to the promoters of epithelial polarity genes and suppresses their transcription, causing breast cancer cells to lose adherence and thus conferring invasive potential." (PMID 35409206, 2022). "In this study, we identified Zeb1 as a key regulator of tumorigenesis-associated metabolic reprogramming by directly targeting glycolytic enzymes in breast cancer." (PMID 35246504, 2022). "Together, ZEB1 is a massive driver of breast cancers causing death, although the regulatory mechanisms of highly expressed ZEB1 in breast cancers remain much less understood." (PMID 34462429, 2021). "The emergence of reversible resistance to targeted therapy such as tamoxifen in ER+ positive breast cancer can be modulated in part by EMT-associated players such as ZEB1, miR-200 and SLUG, by virtue of their crosstalk with the estrogen receptor alpha (ERα)." (PMID 34975907, 2021). "All four molecules, SIX‐1 (AUC = 0.8104, P < .01), lncATB (AUC = 0.8213, P < .01), miR‐200c‐3p (AUC = 0.7896, P < .01) and ZEB1 (AUC = 0.7754, P < .01), have certain diagnostic capabilities for breast cancer." (PMID 32227618, 2020).
breast carcinoma (continued). "Most studies suggest that ectopic ZEB1 is associated with a poor outcome in breast cancer patients based on its role in increasing tumorigenicity and stemness." (PMID 33046710, 2020). "Cullin4A (Cul4A) as an oncogene mediates the EMT process in breast cancer cells, which in turn causes metastasis by modifying the regulatory ZEB1 gene." (PMID 32793473, 2020). "This has recently been explained in human breast cancer and earlier demonstrated in other, like bladder cancers that zinc finger E-box binding homeobox 1 (ZEB1) is associated with the development of epithelial to mesenchymal transition (EMT)." (PMID 32158360, 2020). "ZEB1 has a pivotal role in tumor progression and metastasis and can underlie chemotherapeutic resistance in breast cancer." (PMID 32850701, 2020). "Overexpression of Snail 1, ZEB1, and Twist linked to poor treatment response and acquired resistance in breast cancer through the EMT pathway." (PMID 35582717, 2019). "Together, these data indicate that expression of the ZEB1 transcriptional program is associated with reduced overall survival in breast cancer." (PMID 31780722, 2019). "Surprisingly, high expressions of a cluster of M-genes that are strictly dependent on ZEB1 have significant association with good prognosis in breast cancer patients." (PMID 31275609, 2019). "The results generated by TIP reproduced the results from the xCELL-based approach, increasing our confidence that stroma-corrected ZEB1 expression is indeed associated with decreased immune cell abundance and antitumor immune activity in breast cancer." (PMID 31780722, 2019). "Extrinsic factors, like the multipotent cytokine transforming growth factor β (TGF-β) stimulates EMT in breast cancers and mechanistically, TGF-β stimulation is associated with upregulation of SNAIL, TWIST, ZEB1/2 in luminal A and B breast cancer cell lines." (PMID 31075939, 2019). "Together, our results strongly indicated that stroma-corrected ZEB1 expression is associated with a reduced antitumor immune response in breast cancer." (PMID 31780722, 2019). "ZEB1/2-mediated repression of E-cadherin associated with DNA methylation-regulated silencing of polycomb protein Mel-18 to induce EMT in breast cancer cells." (PMID 35582717, 2019). "Associations between ZEB1 positivity in breast cancer tissues and patient characteristics (n = 257)." (PMID 31331982, 2019). "From these analyses, we concluded that several EMT-TFs are correlated with stromal cell abundance within tumors and that ZEB1 has a particularly strong and reproducible association with tumor stromal content in breast cancer." (PMID 31780722, 2019). "Our analysis of breast cancer cells agrees with this general conclusion, and associates high ZEB1 expression with the basal‐B subgroup of human breast cancers." (PMID 29744893, 2018). "Both lung cancer and breast cancer have been shown to have high levels of ZEB1 expression and are associated with metastasis and poor patient outcome." (PMID 32309604, 2018). "Based on this premise, we analyzed the genome–wide association of ZEB1 and evaluated the loss of function mutation in ZEB1 in breast carcinomas." (PMID 29744893, 2018). "Specifically, BMP6 signaling leads to downregulation of ZEB1 and preservation of epithelial features in breast cancer cells, whereas breast cancer cells undergoing EMT exhibit loss of BMP6 expression due to methylation of DNA sequences on the BMP6 gene." (PMID 29729076, 2018). "The other EMT transcription factor ZEB1 has also been implicated in the promotion of osteolytic bone metastases in breast cancer." (PMID 29088803, 2017). "Here, we report that ectopic zinc-finger E-box binding homeobox 1 (ZEB1) is associated with ER-α deficiency in breast cancer cells and thus confers antiestrogen resistance." (PMID 28383555, 2017). "These experiments strongly indicated that ZEB1 expression caused estrogen independence in breast cancer cells that possibly led to antiestrogen resistance." (PMID 28383555, 2017).
breast carcinoma (continued). "FBXO4 overexpression decreased EMT in metastatic breast cancer cells with a loss of fibronectin, vimentin, and ZEB1." (PMID 29137327, 2017). "Consistent with the relationships between the EMT and cancer malignancy, high expression of ZEB1 is associated with poor prognosis of many types of cancer, including breast cancer." (PMID 28618162, 2017). "We found that the mechanism underlying ZEB1-stimulated angiogenesis is the induction of VEGFA production by breast cancer cells." (PMID 26882471, 2016). "This is also consistent with our observation here that increased tumor development and growth are associated with elevated expression of ZEB1 in animal models of breast cancer." (PMID 26882471, 2016). "Among the different epithelial–mesenchymal transition (EMT)-associated transcriptional factors, ZEB1 has a key role in inducing the mesenchymal phenotypes and stem cell-like properties of different breast cancer cells." (PMID 27617643, 2016). "Among the different EMT-associated transcriptional factors, ZEB1 was previously found to be most crucial in inducing EPB41L5 in breast cancer and renal cancer." (PMID 27871329, 2016). "The induction of EMT in breast cancer cells leads to the down-regulation of Siah, while the loss of Siah induces a mesenchymal phenotype, concurrent with an up-regulation of Zeb1." (PMID 25528765, 2015). "Here we show that the EMT-inducer ZEB1 activates the expression of genes, previously associated with breast cancer bone metastasis, including the BMP-inhibitors NOG, FST and CHRDL1." (PMID 25973542, 2015). "We recently reported increased expression of ZEB1 protein and loss of its target E-cadherin in an endocrine-resistant, ERα+ breast cancer cell line LY2 compared to the parental MCF-7 cell line." (PMID 23626803, 2013). "Our results indicate a role for loss of miR-200 family members and increased ZEB1 in conferring resistance to antiestrogens in breast cancer." (PMID 23626803, 2013). "There was a significant positive association between zeb1 and twist expressions in stromal fusiform cells in breast carcinoma (p < 0.001) with stromal zeb1being significantly lower in ductal in situ carcinomas than in invasive carcinomas (p = 0.020)." (PMID 21324165, 2011). "Stromal zeb1 expression was significantly lower in in situ type of breast carcinoma compared to invasive cases indicating that induction of zeb1 in stromal cells associates with the invasive phenotype." (PMID 21324165, 2011). "We selected five genes (CAV1, DHFR, TYMS, VIM, ZEB1) known to be associated with drug sensitivity and the epithelial-mesenchymal transition of breast cancer." (PMID 21501481, 2011). "We have previously shown that restoration of miR-200c in Hec50 endometrial cells and MDA-MB-231 breast cancer cells causes repression of ZEB1 and re-expression of E-cadherin protein." (PMID 20049172, 2010). "Similarly, dysregulation of aerobic glycolysis, an increase in M2-like TAMs, and poor prognosis are clinically linked to Zeb1 expression in patients with breast cancer." (PMID 39858015, 2025). "Since ZEB1 expression in breast cancer is inversely linked to ERα protein levels, downregulating ZEB1 significantly increases the responsiveness of breast cancer cells to estrogen inhibitor therapy using tamoxifen and fulvestrant under in vitro and in vivo conditions." (PMID 40843360, 2025). "Likewise, ΔNp63 promotes a hybrid EMT state in basal like breast cancer by simultaneously increasing Slug and Axl expression, while also increasing the expression of miR-205 to silence ZEB1/2 for preventing loss of epithelial characteristics." (PMID 37460540, 2023). "Next, we examined the impact of ZEB1 deficiency on EMT in this breast cancer cell line." (PMID 37567892, 2023). "Indeed, elevated ZEB1 levels have been found in several human cancers, such as lung cancer, colon cancer, glioblastoma and breast cancer, which were further associated with advanced disease progression and higher metastatic spreading." (PMID 38139138, 2023).
breast carcinoma (continued). "Moreover, increased ZEB1 expression is associated with tumor grade in LAD and ZEB1 promotes colorectal and breast cancer metastasis." (PMID 36376711, 2023). "Clinically, the expression of Zeb1 is positively correlated with dysregulation of aerobic glycolysis, accumulation of M2-like tumor-associated macrophages (TAMs) and a poor prognosis in breast cancer patients." (PMID 35246504, 2022). "In mesenchymal stem cells, ZEB1-repressed miRNA clusters upregulate secreted fibronectin 1 and serine protease inhibitor family E member 2 to stimulate autocrine signaling, which is associated with increased vasculogenic mimicry in breast cancer cells." (PMID 35454770, 2022). "AKT1-E17K mutation in breast cancer can isolate β-catenin to the cell membrane, which decreases ZEB1 transcription and leads to an increase in E-cadherin expression and the reversal of epithelial-mesenchymal transformation, thus inhibiting tumor migration and invasion." (PMID 36060002, 2022). "We propose that CD151 may be a potential therapeutic target for inhibiting cell proliferation, migration, and invasion of ERα+ breast cancer cells during partial EMT caused by ZEB1." (PMID 35440541, 2022). "Similarly, higher PD-L1 expression was reported in mesenchymal breast cancer cell lines and associated with increased activation of ZEB1 or Snail." (PMID 33810560, 2021). "They predicted potential direct or indirect target genes of the transcriptional repressor ZEB1 and suggested that abnormal expression of the gene set may be a predictor of poor survival, therapy resistance and increased metastatic risk in breast cancer." (PMID 32014049, 2020). "Finally, we evaluated the associations of ZEB1, other EMT-TFs and the ZEB1 program genes with overall survival in breast cancer patients." (PMID 31780722, 2019). "In breast cancer cells, induction of PD-L1, which was suppressed by miR-200, might be caused indirectly by ZEB1, by decreasing miR-200 expression." (PMID 31213009, 2019). "The miR-200c - ZEB1 axis was also linked to invasive activity in breast cancer cells." (PMID 30473751, 2018). "Our data collectively have identified a molecular mechanism underlying ZEB1-mediated chemoresistance, indicating that ZEB1 may be a potential target for breast cancer treatment." (PMID 29352223, 2018). "Notably, the depletion of ZEB1 by RNA interference causes ER-α promoter demethylation, restores ER-α expression, and increases the responsiveness of breast cancer cells to antiestrogen treatment." (PMID 28383555, 2017). "Importantly, in tumors with high ALDH1 activity, we observed increased expression of ZEB1 and decreased expression of NGN3, strongly suggesting that dysregulated ZEB1/NGN3 signaling is functionally linked to tumor stem cell traits in breast cancer." (PMID 28903350, 2017). "We have also shown in the PMC42 human breast cancer model system that cellular proliferation was associated with an epithelial phenotype because the stable knockdown of ZEB1 in PMC42-ET cells resulted in CDH1 reexpression along with an increased proliferative rate." (PMID 28750639, 2017). "It has also been shown that ZEB1, a transcription factor associated with epithelial–mesenchymal transition in cancer progression, is not only a direct transcription repressor of E-cadherin in human breast cancer cell line but also of EpCAM in both human pancreatic and breast cancer cell lines." (PMID 35241091, 2022). "In addition, some studies point out that the up-regulation of EMT-associated transcriptional factors, containing Slug, Zeb1 and Twist1, can directly lead chemotherapy in breast cancer and NSCLC through the ATP-binding cassette (ABC) transporter family of proteins (ABCB1, ABCC1 and ABCG2)." (PMID 33282725, 2020).